CXCL9 (C-X-C motif chemokine ligand 9)
Diseases named in the same sentence as CXCL9 in open-access papers (continued):
Sharing a sentence is not in itself a finding about the gene and the disease.
tumor (continued). "We show here that COX2 expression at the tumor margin limits CD8+ T-cell infiltration into the tumor core, which involves at least in part reduced cytokine and chemokine expression (IRF8, CLEC9a, CXCL9, CXCL10, CXCL11, and IL27) that promotes directional immune cell migration." (PMID 39356141, 2024). "In tumor cells, METTL3 and METTL14 can inhibit the expression of CXCL9 and CXCL10." (PMID 39726589, 2024). "CCL5, CXCL9, CXCL10, CXCL11, and CX3CL1 are involved in the recruitment of CD8+ T cells to tumours." (PMID 38291183, 2024). "Moreover, radiotherapy stimulates the release of chemokines such as CXCL9, CXCL10 and CXCL16 from tumor cells and stromal cells, which increase the infiltration of intratumoral NK, DC, and T cells, leading to enhanced anti-tumor immunity." (PMID 39712010, 2024). "In addition, EZH2 also promotes the transition of TAMs to the M2 phenotype and inhibits the Th1-type chemokine C-X-C Motif Chemokine Ligand 9 (CXCL9) to reduce CD8+ T cell infiltration, thereby reducing the anti-tumor immune response." (PMID 39227959, 2024). "For example, CXCL9 and CXCL10 are two important chemokines that are involved in antitumor immunity by binding to their receptor, CXCR3, which promotes the migration of T cells and NK cells into the tumor microenvironment." (PMID 39334957, 2024). "IFNγ-inducible chemokines CXCL9 and CXCL10 are ligands for CXCR3, a receptor expressed by diverse immune populations and reported to play important roles in immune cell recruitment and tumor immunity." (PMID 38454126, 2024). "EZH2-mediated DNA methylation associated with DNMT1 and H3K27me3 may inhibit the expression of the type 1 T helper cell (TH1) chemokines CXCL9 and CXCL10, as well as the subsequent transport of effector T cells to the tumor microenvironment." (PMID 38665224, 2024). "Indeed, macrophage positivity for CXCL9 or SPP1 defined anti- and pro-tumor macrophage phenotypes better than classical M1/M2 hallmarks expression." (PMID 38542388, 2024). "It has been shown that inhibition of tumor acidosis by adenylyl cyclase inhibitor MDL-12 induces NOS, CXCL9, CXCL11, and TNF-α-expressing proinflammatory TAMs that are phenotypically similar to classical M1 macrophages, leading to suppression of tumor growth in B16 mouse melanoma." (PMID 39003350, 2024). "Epi_Cxcl9, which is essentially absent in normal samples but highly enriched in OSCC_1, represents a tumor‐specific cell type." (PMID 38962427, 2024). "However, prolonged exposure to interferon-gamma transforms teammates into adversaries, producing pro-tumorigenic effects through immunosuppression (PDL1, IDO1, Fas, and FASL), angiogenesis (CXCL9, CXCL10, CXCL11, IDO1, and iNOS), and tumor cell proliferation." (PMID 39835116, 2024). "In addition, C-X-C motif chemokine ligand 9 (CXCL9) and CXCL10 are critical for CD8+ T cell infiltration into the tumor site to facilitate a productive antitumor response." (PMID 39034411, 2024). "Additionally, another key finding of this study was that ONB with high intra-tumoral CD8+ T cell infiltrates demonstrated significantly higher CXCL9 and CXCL10 tumor cell expression." (PMID 38822345, 2024). "Through animal and cell experiments, we found that NE can affect the secretion of the chemokine CXCL9 and the immunosuppressive metabolite ADO in tumour cells by regulating the WNT7A/β-catenin signalling pathway, thereby inhibiting chemotaxis and function of CD8+ T cells." (PMID 36646807, 2023). "For example, NK cells can be recruited by C-X-C motif chemokine ligand 9 (CXCL9), produced in activated CD103+DCs (dendritic cells), into the tumor microenvironment to express granzyme B, interferon-gamma (IFN-γ), and tumor necrosis factor-alpha (TNF-α) to kill HCC cells." (PMID 37239062, 2023). "Tumorigenesis increased the frequency of cDC2s that were producing Cxcl10 or Cxcl9 and Cxcl10 in the dLN and tumor, yet not the spleen." (PMID 36472588, 2023).
tumor (continued). "We examined AAV delivered CXCL9 transgene tropism, durability, and impact on CTL tumor migration." (PMID 38014191, 2023). "Following a comprehensive chemokine screen of clinical tumor specimens, we have identified CXCL9 as a candidate lymphocyte call-and-receive signal absent in GBM." (PMID 38014191, 2023). "Recently, it was reported that macrophage polarity defined by CXCL9 and OPN expression, rather than traditional M1 and M2 markers, was strongly associated with tumor prognosis." (PMID 38250077, 2023). "In a prior study, Cxcl9 but not Cxcl10 expression by cDC1s was critical for αPD-L1 efficacy which was attributed to intratumoral T cell trafficking toward cDC1s in the tumor bed in s.c. implantable tumor models." (PMID 36472588, 2023). "The CXCL9, 10, 11/CXCR3 axis have both anti-tumor and pro-tumor activity." (PMID 37465363, 2023). "These populations have been described to have direct tumor-killing capacities as well as to promote CD8+ T cell activation, via amongst others, expression of T cell-recruiting and activating chemokines such as CXCL9 and increased antigen presentation capacity." (PMID 37089449, 2023). "CXCL9 and CXCL10 also have the function of inhibiting endogenous tumor angiogenesis." (PMID 37046739, 2023). "Additionally, M1-polarized macrophages can recruit new Th1 cells via IFN-γ and chemokines CXCL9 and CXCL10 to kill tumor cells." (PMID 38001420, 2023). "However, it has been well documented that CXCL9, 10, and 11 play crucial roles in immune activation and tumor rejection in TME via its cognate receptor, CXCR312, and anti-tumor effect of anti-PD-1 therapy decreases in CXCR3 knock-out mice." (PMID 36991099, 2023). "Th1 T cells may also amplify tumor immune defenses via the recruitment of cytotoxic leukocytes and the secretion of chemokines, including CXCL10 and CXCL9." (PMID 37766141, 2023). "Indeed, it has been reported that the chemokine ligands CXCL9, 10, 11, and 16 as well as CX3CL1 are responsible for recruiting T cells and natural killer (NK) cells into the tumor." (PMID 37443821, 2023). "Indeed, the co-expression of Oct4/Sox2 inhibits the expression of the C-C Motif Chemokine ligand 5 (CCL5) and C-X-C Motif Chemokine ligand 9, 10 and 11 (CXCL 9,10 and 11), which mediate CD8+ T cell attraction against tumor cells." (PMID 36831383, 2023). "Brain tissue and serum were also collected from non-transduced (sham) tumor controls, and naïve (non-tumor bearing) controls to establish CXCL9 baseline values." (PMID 38014191, 2023). "In general, CXCR3 is highly expressed on the surface of NK cells, and it drives NK cell-specific chemotaxis toward the CXCR3 ligands CXCL9, CXCL10 and CXCL11, which are secreted by tumor cells into TME and usually expressed at relative low levels in homeostatic condition." (PMID 38264648, 2023). "It hinted that CXCL9 may serve as an independent prognostic biomarker or therapeutic target in UCEC patients, which augmented anti-tumor immune effects to furnish survival benefits." (PMID 36845675, 2023). "In the tumor context, the production of prostaglandin E2 (PGE2) by tumor cells leads to cDC1 dysfunctionality marked by the downregulation of IRF8, and key effector cytokines such as CXCL9 and IL-12, resulting in poor CD8+ T cell tumor infiltration and ultimately in tumor immune evasion." (PMID 37520521, 2023). "Tumours from patients with durable responses are enriched for PDL1+ CXCL10+ macrophages and, based on cell–cell interaction analysis, express high levels of CXCL9/10/11 and are predicted to attract peripheral CXCR3+ CD8+ effector-memory T cells (CD8 TEM) into the tumour." (PMID 38030622, 2023). "In addition, CXCL9, a ligand of CXCR3 that promotes adhesion to vascular endothelium for CXCR3, promotes the release of IFN-ɤ from CD8-positive T cells in the tumor by anti-VEGF antibody and anti-PD-1 antibody." (PMID 37046727, 2023).
tumor (continued). "Moreover, the tumor cell-derived CXCL6, CXCL2, and CCL20, TAM-derived CXCL9/CXCL10, and the stromal cell-derived CXCL12 also contributed to the accumulation of tissue-resident CD103+CD8+TILs in the TME." (PMID 37024870, 2023). "One pathway that appears to be strongly involved in DCI is the type I interferon pathway, which is involved in the secretion of cytokines and immunomodulatory chemokines (CXCL9, CXCL10) that bind to the CXCR3 receptor and in the recruitment of CD8+ T cells to the tumor microenvironment." (PMID 37108738, 2023). "CXCL9 and CXCL16 are chemokines involved in recruiting T cells and facilitating tumor infiltration." (PMID 38137547, 2023). "We hypothesized that AAV delivery and restoration of CXCL9 as a “call-and-receive” signal for T lymphocytes within the TME would enhance their recruitment and infiltration in the tumor." (PMID 38014191, 2023). "Although the exact role of eosinophils in cancer is not fully understood, some studies suggest they contribute towards anti-tumor immunity by inducing tumor death via the production of anti-tumor factors such as TNF-α, along with recruiting CD8+ T cells into tumors via CXCL9 and CXCL10 release." (PMID 38137547, 2023). "The T-cell chemoattractant CXCL9 was previously found elevated in CRC tissues compared to normal colon tissues and it was associated with tumor differentiation and invasion, lymph node and distant metastasis, as well as with vascular invasion." (PMID 37228491, 2023). "CXCL-9 is an IFN-γ inducible chemokine that attracts various CXCR-3-expressing effector immune cells including CD8+ and CD4+ T-cells and also NK cells, and thereby changes the tumor microenvironment to an anti-tumor phenotype." (PMID 37958417, 2023). "Some of the chemokines, including the platelet factor 4 (PF4), the C-X-C motif chemokine ligand 9 (CXCL9), and CXCL10, may inhibit tumor vessel formation." (PMID 38001676, 2023). "Conversely, ARID1A, a core member of the SWItch/Sucrose Non-Fermentable (SWI/SNF) complex, promotes tumor expression of CXCL9 and CXCL10." (PMID 36600243, 2023). "In conclusion, the anti-tumor effects induced by anti-PD-1 antibody treatment were found to be attenuated in STZ-induced diabetic mice, which was accompanied by decreased infiltration of CD11c+ cells and CD8+ T cells and decreased expression of CCL7 and CXCL9." (PMID 37046033, 2023). "These spots also upregulated the chemokines CXCL9 and CXCL12, which could attract T cells into the tumor via CXCR3 and CXCR4, respectively." (PMID 37655659, 2023). "The upregulation of pro-inflammatory cytokines can also lead to the production of IFNγ which can induce chemokines CXCL9 and CXCL10 to recruit NK cells, neutrophils, macrophages, and T cells to the tumor and stimulate acquired immunity for a tumor-specific response." (PMID 37588093, 2023). "Thus, the relationship between CXCL9, CXCL10, CXCL11/CXCR3 axis and tumor development or patient prognosis is still controversial." (PMID 38264648, 2023). "While we show that AAV6 delivered CXCL9 transgene expression predominantly emanates from tumor-reactive astrocytes, our scRNAseq data shows that each anti-PD-1 and AAV gene therapy induces CXCL9 transcription within CD8 T cells, additionally demonstrating immune activation as a result of treatment." (PMID 38014191, 2023). "In addition, M1 macrophages secrete CXCL9, CXCL10 and CXCL15 chemokines upon STAT1 signaling, which recruit cytotoxic T lymphocytes (CTLs) to the tumor." (PMID 36311701, 2022). "Our data revealed that the addition of TIGIT blockade to MWA upregulated the expressions of CXCL9 and CXCL10 in TAMs and the expression of their receptor CXCR3 in T cells, which might restrain tumor growth and enhance antitumor immunity." (PMID 35320940, 2022).
tumor (continued). "The collective evidence therefore suggest that SPATA2 over-expression is associated with a non-T-cell-inflamed TME in CRC, and that SPATA2 might mediate T cell exclusion by inhibiting the production of CXCL9, CXCL10, and CXCL11 from tumor cells." (PMID 36531014, 2022). "Furthermore, the quantity of lymphocytes in the tumor samples analyzed with flow cytometry positively correlated with the chemokine-family of cytokines, CXCL10 (IP-10) and CXCL9 (MIG)." (PMID 35927313, 2022). "Depletion of METTL3 or METTL14 in tumor cells increased cytotoxic tumor-infiltrating CD8+ T cells and elevated secretion of IFN-γ, CXCL9, and CXCL10 in the TME, thereby enhancing the response to anti-PD-1 treatment in mismatch-repair-proficient or microsatellite instability-low CRC tumors." (PMID 35296338, 2022). "We also investigated the specific association between FAM46C expression and chemokines and their receptors in pan-cancer and found that FAM46C expression was positively correlated with immune chemokines (CXCL9 and CXCL13) and immune chemokine receptors (CCR2 and CCR4) in most tumours (all p < 0.01)." (PMID 35222533, 2022). "The use of epigenetic modulators (DNA methylation and H3K27 trimethylation inhibitors) restored the tumoural expression of CXCL9 and CXCL10, enhancing CAR T cell efficacy in a murine model of ovarian cancer, with improved T cell infiltration and tumour growth control." (PMID 35205725, 2022). "Finally, a single injection of cyclophosphamide, a drug able to induce ICD, can increase the Cxcl9, Cxcl10 and Cxcl11 expression within mastocytoma tumors (an effect dependent on CD4 T cells), thus allowing the recruitment of CD8 T cells and tumor regression." (PMID 36429101, 2022). "To summarize, TDO2+ myofibroblasts were mainly located distally from tumor nests, and these cells attracted CD4+ T cells and CD8+ T cells through the CXCL9/CXCL10/CXCL11/CXCR3 axis, which may have prevented T cells from accessing tumor nests." (PMID 35972800, 2022). "Since CXCR3 can bind to its ligands CXCL9, CXCL10, and CXCL11 to inhibit angiogenesis, CXCR3 may play an important role in wound healing and tumor growth." (PMID 36421704, 2022). "CXCL9 and CXCL10 are involved in CD8+ T cells infiltrating into tumor tissues." (PMID 35359417, 2022). "CXCL9, CXCL10, CXCL11 and CCL8 levels were positive correlated with a higher ratio between CD8+ T cells in tumor areas and the total stroma, they might affect the spatial distribution of CD8+ T cells in human pancreatic tumor tissues." (PMID 36479091, 2022). "In addition, CXCL9- and CXCL10-expressing Macro-2 tumor cells interact with CXCR3-expressing proliferating T cells, Tregs, and CTL-1 cells in the tumor." (PMID 36180422, 2022). "CXCL9/10/11 are ligands for CXC-chemokine receptor 3 (CXCR3), which is highly expressed on cytotoxic CD8+ T cells and IFN-γ-producing CD4+ T helper 1 cells, both of which provoke tumor cell killing and enhance inflammation in the TME." (PMID 36531014, 2022). "IL-16, TGF-β3, CXCL9, and SCF were the best contributors to this tumor signature." (PMID 36539890, 2022). "CD103+ DCs are usually necessary to recruit CD8+ T cells through CXCL9; failure to promote their recruitment in patients of β-catenin high tumors renders these resistant to anti-PD-1 blockade therapy or abrogate treatment effects of ACT in murine tumor models." (PMID 36366354, 2022). "Comparing immune cells and immune-related gene expression across different FAT statuses, we found that in FAT mutant STAD, chemokines, such as CCL3, CCL4, CXCL1, CXCL3, CXCL9, and CXCL10, recruited and activated cytotoxic T lymphocytes in the tumor tissue to perform an antitumor effect." (PMID 35836939, 2022). "Furthermore, CXCL9 has been proposed as a therapeutic for EOC due to its ability to inhibit angiogenesis and promote anti-tumor immunity." (PMID 35269786, 2022). "CXCL9 was upregulated 24 hours after vaccination in myeloid cells, especially macrophages, but not lymphocytes or tumor cells." (PMID 35623658, 2022).
tumor (continued). "We, therefore, hypothesize that CXCL9/10 signaling via CXCR3 may impact the microenvironment and potentially promote tumor progression through deregulation of inflammatory pathways." (PMID 36180422, 2022). "As for the genes regulated by EBV-miRNAs, the CXCL9, CXCL10, CXCL11/CXCR3 axis has been found to regulate immune cell migration, differentiation, leading to tumor suppression and may have potential role in cancer treatment." (PMID 36544484, 2022). "(ii) Antitumor immune-related molecules including CXCL10, CXCL9, CXCR3, CCL5, and CCL4 belong to the chemokine family and have been reported in several studies to recruit immune cells such as cytotoxic T lymphocytes (CTL) and NK cells to kill tumor cells." (PMID 35479936, 2022). "Recently, macrophage-expressing C-X-C motif chemokine receptor 3 (CXCR3) ligands including CXCL9 were found to recruit CD8-positive T cells and be indispensable for anti-tumour efficacy of ICIs, suggesting the importance of cytocidal macrophages working against both tumour cells and beta cells." (PMID 35511238, 2022). "Moreover, KDM6B inhibit CXCL9 and CXCL10 expression in colon cancer and exerts an anti-tumor immune effects." (PMID 36713412, 2022). "Anti-PD-1 therapy did not enhance the anti-tumor response in Cxcr3−/− mice that were non-responsive to CXCL9/10." (PMID 35806328, 2022). "Similar observations were made when only the ccRCC cases were included; significant positive correlations were observed for both CXCL10 and CXCL9 with the tumor lymphocytes and CD3 + T cells, respectively, but not with the NK cells (Supplementary S5Bi-vi)." (PMID 35927313, 2022). "In this context, for the first time, we found that GSK343 treatment was able to modulate the innate immune response, increasing CXCL9, CXCL10 and CXCL11 levels in GB, as a result of EZH2 inhibition, enhancing NK cell migration to tumor sites and consequently NK cell-mediated tumor growth inhibition." (PMID 36430394, 2022). "We found that cyclin G2 increased CXCL9 production and secretion from macrophages after IFN-γ treatment, which could explain the effects of cyclin G2 on CTL recruitment and tumor angiogenesis." (PMID 36566226, 2022). "However, several studies have shown that PD-L1 expression can be upregulated on various types of tumor cells by the activation of the STAT3 and PI3K-Akt pathways when CXCL9 is stimulated by IFN-gamma signaling." (PMID 36362062, 2022). "We further found that tumor-rich tissues produced higher levels of CXCL9, CXCL10 and CXCL11 compared to nontumor tissues." (PMID 35954489, 2022). "The authors found that the co-expression of CCL5 and CXCL9 could promote CD8+ T cells infiltration, prolong survival, and alleviate reactivity to PD-1 inhibitors in tumor tissue." (PMID 35892835, 2022). "qRT-PCR showed that L. paracasei sh2020 made a drastic increase in the level of CXCL10 in tumor tissue, whereas no changes were found in CXCL9, and CXCL11." (PMID 35259052, 2022). "These include plasmid-borne CXCL9, intra-tumor injection of CXCL9, recombinant CXCL10 protein with adoptive cell therapy (ACT), intra-tumor injection of CXCL10, retroviral transduction tumor cells with CXCL10, and intraperitoneal injection of oncolytic vaccinia virus expressing CXCL11." (PMID 33603130, 2022). "Tumor-intrinsic T-cell-exclusionary pathways typically converge on a repression of type I and/or II interferons (IFNs), and thence a paucity of IFN-induced T cell chemokines such as CXC-chemokine ligand 9 (CXCL9), CXCL10, and CXCL11 in the TME." (PMID 36531014, 2022). "Additionally, the levels of the chemokines CXCL9 (MIG, p < 0.0001, median 54.3 pg/mL vs 7.0 pg/mL) and CXCL10 (IP-10, p = 0.0021, median 92.9 pg/mL vs 16.7 pg/mL) were also increased in the tumor samples compared to the healthy tissues." (PMID 35927313, 2022). "Furthermore, expression of multiple T-chemo-attractants, including CXCL9 and CXCL1049, is also markedly induced in Mll4−/− tumor cells and bulk tumors." (PMID 36323669, 2022).